CUL1 (cullin 1)
Diseases named in the same sentence as CUL1 in open-access papers (continued):
Sharing a sentence is not in itself a finding about the gene and the disease.
thyroid cancer (1 paper, 2024). "These hub genes identified in our study have implications for the response to immune checkpoint inhibitors therapy (PRKDC) and offer potential prognostic markers (CUL1, VAV2), presenting a novel avenue or additional treament for thyroid cancer therapeutics." (PMID 39013964, 2024).
tuberculosis (1 paper, 2021). A chronic, recurrent infection caused by the bacterium Mycobacterium tuberculosis. "Mycobacterium tuberculosis, the causative agent of tuberculosis, was shown to increase neddylation of cullin-1 from dendritic cells (DC) to evade innate immune defenses via inside-out signaling." (PMID 34499701, 2021).
urothelial carcinoma (1 paper, 2025). A malignant neoplasm derived from the transitional epithelium of the urinary tract (urinary bladder, ureter, urethra, or renal pelvis). "Of the proteins shared by networks A and C, the 2 PPI networks specific to papillary urothelial carcinoma, CDC5L and CUL1, have been found to be upregulated in urothelial carcinoma in previous studies." (PMID 41342186, 2025).
Usher syndrome (1 paper, 2016). A syndromic diseae characterized by the association of sensorineural deafness (usually congenital) with retinitis pigmentosa and progressive vision loss. "We also tested whether a second Usher syndrome homologue, Sans, interacts with Ubr3 and Cul1." (PMID 27331610, 2016).
uterine cancer (1 paper, 2021). Primary or metastatic malignant neoplasm involving the uterine corpus and/or the cervix. "Conversely, CUL1 exhibits a higher mutational load in some cancers, as evidenced by the 23 and 35 mutations observed in stomach and uterine cancers, respectively." (PMID 35008511, 2021). "Overall, the methylation status of CUL1 is very similar to that of SKP1, as tumor samples with copy number losses also tend to be hypermethylated; however, CUL1 is generally partially methylated or hypermethylated in all uterine cancer cases." (PMID 35008511, 2021).
tumor (31 papers, 2007 to 2026). "Compared to parental SK-KOSA cells, mtDNA depletion in SK-KOSA cells resulted in higher levels of the markers β4 Integrin, Cullin-1 and Ezrin suggesting a causal role of mtDNA depletion in the induction of the marker genes that drive tumor progression." (PMID 30576337, 2018). "MLN4924 treatment rapidly blocked neddylation of cullin 1 and cullin 2, two tumor-associated cullin family members." (PMID 27223074, 2016). "rs76011559 lies upstream of CUL1 and replicated as a prognostic biomarker in patients with proximal tumours." (PMID 39827162, 2025). "In contrast, the mice injected with mEERL/Cul1 or mEERL/Ube2l3 cells displayed delayed tumor formation and death by tumor burden." (PMID 38226814, 2024). "The results indicated that in comparison to the paired adjacent non-tumor tissues, Cul1 expression was evidently increased in HCC tissues." (PMID 37771770, 2023). "In agreement with the most prevalent copy number alterations detailed above, SKP1 mRNA expression levels are often reduced within tumor samples relative to normal tissues, whereas CUL1 expression is frequently increased." (PMID 34445249, 2021). "Tumor cells harboring CUL1-BRAF fusion have been found to show activation of MAPK signaling pathway and sensitivity to MEK/RAF inhibition." (PMID 34657620, 2021). "The CUL1 gene was significantly downregulated in baseline samples of patients with pCR as compared to those with residual tumor (unadjusted p < 0.01)." (PMID 33428680, 2021). "A reduced macrophage recruitment was mediated by a reduced chemotaxis factor CCL2 production of tumor cells resulting from a nuclear factor- κB (NF-κB) pathway blockade mediated by CUL1 inhibition." (PMID 33233664, 2020). "In fact, FBXW7 is a well-known tumor suppressor that functions as a substrate-recognition protein within a SCF (SKP/CUL1/F-Box) E3 complex ubiquitin ligase complex, which targets numerous proteins for ubiquitin-mediated proteasomal degradation." (PMID 31351478, 2019). "Using intravenous tumor metastasis model and angiogenesis in vivo, we indicated that CUL1 knockdown significantly reduced the lung metastasis and angiogenesis." (PMID 30578411, 2018). "Tumours were excised at the end of the study and the effect of compound treatment assessed on the pharmacodynamics markers, neddylated Cul1 and Skp2." (PMID 27774986, 2016). "In line with the anti-tumour efficacy, Cul1 deneddylation was inhibited and Skp2 levels were reduced in the tumours of the treated mice but not in those from vehicle controls." (PMID 27774986, 2016). "Unexpectedly, analysis of the data indicated that key effectors of the cell cycle like cyclin D1, cyclin E1, growth arrest and DNA damage, and cullin 1, were the primary targets of the transcriptional modifications imposed on these tumor cells." (PMID 23646174, 2013). "Interestingly, cell division cycle (CDC6), a critical molecule assisting tumor cells in resisting radiation, is degraded via the CUL1 neddylation-mediated ubiquitin-proteasome pathway, indicating that neddylation also contributes to radiosensitization." (PMID 41540013, 2026). "Notably, transcriptomic data and RTqPCR results demonstrated that while PUM2 and HIF3A were highly expressed in normal tissues, DDB1 showed increased expression in tumor tissues, with CUL1, COPS2, and UBE2D3 remaining unchanged." (PMID 40524221, 2025). "To determine whether Cul1 and Ube2l3 overexpression suppresses HPV+ HNC tumor growth, we generated mEERL cells overexpressing Cul1 (mEERL/Cul1) or Ube2l3 (mEERL/Ube2l3) using lentiviruses and blasticidin selection." (PMID 38226814, 2024). "CUL1 activity can perform tumor-suppressive functions in cells." (PMID 39588388, 2024). "Collectively, these findings support the possibility that SKP1, CUL1, and RBX1 encode tumor suppressor- or oncogene-like activities depending on whether they are under- or over-expressed." (PMID 34445249, 2021).
tumor (continued). "Interestingly, 32 of the 130 predicted SLIs occurred with FBXW7, a well-known tumor suppressor that functions as a substrate-recognition protein within a SKP/CUL1/F-Box ubiquitin ligase complex for proteasome degradation." (PMID 31351478, 2019). "Upregulating wild-type hMEPE/OF45 (but not mutant hMEPE/OF45) could stabilize CHK1 by reducing CHK1 interaction for its E3 ligases Cul1 or Cula4A; it increases the G2 checkpoint response and increases the resistance of tumour cells to IR or CPT treatment." (PMID 20145617, 2010). "Also, Cul1 staining was apparently connected with tumor size, TNM stage and histology grade." (PMID 37771770, 2023). "The S-phase kinase-associated protein 1 (SKP1)-cullin-1 (CUL1)-F-box-protein (SCF) complex belongs to the really interesting new gene (RING) family of E3 ubiquitin ligases, mediating the degradation of ~20% proteins related to cell-cycle regulation, transcription, oncogenesis, and tumor suppression." (PMID 35515121, 2022). "Among them, compound 27 exhibits 25-fold greater potency than the initial hit, effectively stabilizing DCN1 and specifically decreasing the CUL1 and CUL3 neddylation levels in tumor cells." (PMID 41540013, 2026). "Transcriptomic profiling of TCGA datasets revealed significant up-regulation of CUL1, CUL2, CUL4A, CUL4B, CUL5, CUL7, and CUL9 in tumor tissues, with higher expression correlating with advanced stage and poorer survival, particularly for CUL5 and CUL7." (PMID 42021323, 2026). "These analogs selectively decline CUL1 and CUL3 neddylation levels, demonstrating the potential for anti-tumor activity." (PMID 41540013, 2026). "Our results suggest that Cul1 or Ube2l3 overexpression results in HPV16 E7 protein degradation and tumor suppression." (PMID 38226814, 2024). "Conversely, the overexpression of CUL1 and UBE2L3 in HPV+ HNC cells decreases HPV16 E7 protein levels and suppresses tumor growth in vivo." (PMID 38226814, 2024). "To investigate if the degradation of HPV16 E7 protein by CUL1 and UBE2L3 inhibits tumor growth, we utilized a C57BL/6J (B6) mouse oral epithelial (MOE) cell line expressing HPV16 E6/E7 and Hras (mEERL) which forms tumors in immunocompetent syngeneic B6 mice." (PMID 38226814, 2024). "Conversely, overexpression of CUL1 and UBE2L3 in HPV+ HNC cells decreases HPV16 E7 protein levels and suppresses tumor growth in vivo." (PMID 38226814, 2024). "The expression levels of CUL1, NR1D1, and PER2 were lower in tumor deletion samples than in other tumor and normal tissue samples." (PMID 36439444, 2022). "Several critical proteins in tumor development and progression, such as PTEN, MAPK8, CUL1, and RAC3, were enriched." (PMID 35990607, 2022). "Using GO biological process enrichment analysis, we found that CUL1, CUL3, RNF2, and RPA2 overlap in their mitotic cell cycles, which has important biological implications in tumor development." (PMID 32170141, 2020). "Moreover, gossypol, a natural compound derived from cottonseed, hinders the neddylation of CUL1 and CUL5 by directly binding to the RBX1-CUL1 or SAG-CUL5 complex, contributing to NOXA and MCL1 accumulation and tumor growth inhibition." (PMID 41540013, 2026). "Moreover, NAE1-mediated neddylation of CUL1 upregulates vascular endothelial growth factor C (VEGF-C) by augmenting NF-κB transcriptional activity, thereby facilitating tumor angiogenesis and uveal melanoma hepatic metastasis." (PMID 41540013, 2026). "Transcriptomic data and RT-qPCR findings indicated that PUM2 and HIF3A exhibited high expression levels in normal tissues, while DDB1 showed increased expression in tumor tissues; no significant changes were observed for CUL1, COPS2, and UBE2D3." (PMID 40524221, 2025). "Additionally, overexpression of CUL1 or UBE2L3 decreases E7 protein levels and suppresses in vivo tumor growth." (PMID 38226814, 2024). "Additionally, our results show that CUL1 overexpression in HPV+ HNC cells hinders cell proliferation and delays tumor growth in vivo." (PMID 38226814, 2024).
tumor (continued). "In tumour cells in which the KEAP1-CUL3 ubiquitin ligase is unable to repress NRF2, stimulation of GSK3 activity has been found to suppress NRF2, presumably by increasing ubiquitination of the CNC-bZIP transcription factor by β-TrCP-cullin-1." (PMID 29102676, 2018).
cancer (28 papers, 2013 to 2026). A tumor composed of atypical neoplastic, often pleomorphic cells that invade other tissues. "FBXO6 (F-box protein 6, FBG2) is a substrate recognition component of certain SCF (SKP1, CUL1, and F-box protein)-type E3 ubiquitin ligases involved in the degradation of ER-associated proteins, and its role in cancer is highly complex." (PMID 36147499, 2022). "More specifically, the aberrant expression and function of the SCF (SKP1, S-phase Kinase associated Protein 1; CUL1, Cullin 1; F-box protein) complex occurs in an extensive array of cancer types." (PMID 35008511, 2021). "Finally, the results of this study may have far-reaching implications beyond HGSOC, as heterozygous loss of SKP1 or CUL1 occurs in at least 12 common cancer types, although this remains to be empirically determined." (PMID 33731859, 2021). "RNF168, RNF126, and CUL1 are involved in several cellular functions which are critical for the hallmarks of cancer." (PMID 37760968, 2023). "As with SKP1, most CUL1 alterations only occur within a given cancer type with the exceptions of E485K (bladder; head and neck; pancreatic; uterine) and Q607H/K (bladder; skin)." (PMID 35008511, 2021). "Patient-based data from The Cancer Genome Atlas (TCGA) provides further evidence supporting the possibility that aberrant expression and/or function of the core SCF complex components (SKP1, CUL1, and RBX1) have pathogenic roles in cancer." (PMID 34445249, 2021). "While genetic alterations or misregulation of the individual F-box proteins are associated with genomic instability and cancer pathogenesis, less is known about the tumorigenic roles of the invariable SCF components SKP1, CUL1, and RBX1." (PMID 34445249, 2021). "F-box proteins, as substrates for S phase kinase-associated protein 1 (SKP1)-cullin 1 (CUL1)-F-box protein (SCF) ubiquitin ligase complexes, mediate the degradation of a large number of regulatory proteins involved in cancer processes." (PMID 32984335, 2020). "Among the Cullion family, Cullin 1 (CUL1) is one of the scaffold proteins in E3 ubiquitin ligase involved in cancer progression." (PMID 32170141, 2020). "At the same time, CUL1 is also a cancer-related gene which has attracted wide attention in the academic circles in recent years." (PMID 32565880, 2020). "As a key member of SCF, CUL1 is over-expressed in many kinds of cancer and represent as target molecular for therapy." (PMID 27769200, 2016). "For example, overexpressed Cul1 promotes cancer cell proliferation and predicts poor prognosis, while alterations in the Cul1 neddylation/deneddylation pathway contributes to the development of highly aggressive lung tumors." (PMID 26474281, 2015). "For example, Cul1 is increased in melanoma and breast and lung cancers, and is able to promote cancer cell proliferation." (PMID 26474281, 2015). "Additionally, CUL1 augments cancer cell proliferation, adhesion, migration, and metastasis (54, –, 59)." (PMID 38226814, 2024). "Likewise, several cancers, including chronic myelogenous leukemia and testicular cancer, exhibit decreases in CUL1 expression." (PMID 34445249, 2021). "Collectively, these data suggest that while complete loss of SKP1 or CUL1 expression may not be compatible with cell viability (i.e., essential genes), reduced SKP1 or CUL1 expression may have potential roles in cancer initiation." (PMID 33731859, 2021). "The current study builds upon that model by showing that reduced degradation of Cyclin E1 stemming from a diminished expression of SCF complex components, namely SKP1 and CUL1, is an additional mechanism by which Cyclin E1 levels may increase in cancer cells." (PMID 33731859, 2021). "CUL1 plays a role in different cancer signaling cascades and in cell cycle progression." (PMID 29572294, 2018).
cancer (continued). "This fits with our data indicating that EWS-FLI1 is direct enhancer of CUL1 and may be of particular interest in the context of cancer." (PMID 23935076, 2013). "Beyond somatic mutations, SKP1, CUL1, and RBX1 gene copy number alterations including deep deletions (loss of 2 alleles), shallow deletions (loss of 1 allele), gains (gain of 1 allele), and amplifications (gain of ≥2 alleles) are frequently observed in all 12 cancer types." (PMID 34445249, 2021). "Previous genetic studies have shown that heterozygous knockout of SKP1, CUL1, RBX1 and FBXO7 induces CIN, an enabling hallmark of cancer frequently associated with cellular transformation, drug resistance, metastasis and poor patient prognosis in many cancer types." (PMID 35008511, 2021). "However, expression of cullin-1 appeared to be comparable between normal and cancer cells." (PMID 27063292, 2016). "MARCHF8 knockout restores CUL1 and UBE2L3 expression, decreasing E7 protein levels and inhibiting the proliferation of HPV-positive cancer cells." (PMID 38226814, 2024). "A pan-cancer analysis by the ICGC/TCGA 2020 using cBioPortal shows that CUL1 is altered in 9% of the samples, the majority of these being amplification and mRNA upregulation." (PMID 37760968, 2023). "This evidence demonstrates that the SCF complex, especially that of CUL1 and FBXW7, is worthy of continuous investigation for the development of cancer-targeting therapy." (PMID 37760968, 2023). "RNF126, RNF168 and CUL1 are involved in DNA damage response (DDR), DNA double-strand break (DSB) repair, cell cycle regulation, and ultimately, cancer cell proliferation control." (PMID 37760968, 2023). "In several human cancer cell lines, gossypol has been found to block the neddylation of cullin enzymes (CUL5 and CUL1) by directly binding to the SAG-CUL5 or RBX1-CUL1 complex." (PMID 38098026, 2023). "This section discusses ubiquitin pathway-targeting drugs and some of the strategies for the development as well as the potential utilization of RNF126, RNF168 and the CUL1 and SCF complex and its related factors for cancer therapy and diagnostics." (PMID 37760968, 2023). "Next, CNA analyses revealed that each gene is frequently altered in 10 common cancer types, and that SKP1, RBX1, FBXW7 and FBXO5 tend to exhibit more losses, while CUL1 and SKP2 exhibit more gains." (PMID 35008511, 2021). "Elevated expression of CUL1 and CUL4A is observed in cancers, and UBE2M expression is elevated upon irradiation in cancer cells, suggesting the UBE2M-Cullin components are required for survival of the cancer cells." (PMID 25025768, 2014). "The third approach includes inhibiting enzymatic function, blocking PPI or other mechanisms, which might be the desired mechanism for cancer therapy when considering the role of RNF126, RNF168, and CUL1." (PMID 37760968, 2023). "Interestingly, when shallow deletions or gains of SKP1, CUL1, and RBX1 are assessed concurrently within three commonly diagnosed cancers, there is a compounding effect." (PMID 34445249, 2021). "To gain novel insight into cancer pathogenesis, we determined the prevalence of genetic and epigenetic alterations in six prototypic SCF complex member genes (SKP1, CUL1, RBX1, SKP2, FBXW7 and FBXO5) from patient datasets extracted from The Cancer Genome Atlas (TCGA)." (PMID 35008511, 2021). "Stable depletion of SKP2, CUL1, or CDK2 rescued sensitivity to Wee1 inhibition in breast and ovarian cancer cell lines, indicating that cancer patients with overexpression of these G1/S regulatory genes could respond robustly to Wee1 inhibitors." (PMID 34671620, 2021). "CUL1 and c-MYC both show synergistic function in cancers and can act as oncogenes." (PMID 32811853, 2020). "Therefore, our data suggested that the activation of PI3K and its downstream effector AKT by CUL1-induced CXCL8 and IL11 may play a role in cancer metastasis." (PMID 30578411, 2018).
cancer (continued). "Ubiquitin‐regulated signaling was represented with several relevant examples, most notably with the oncogene CBL and with the CUL1 and CUL4B homologs that are not yet in the Cancer Gene Census." (PMID 29572294, 2018). "However, depletion of Cullin 3, but not Cullin 1, elevated the protein abundance of endogenous HDAC6 in multiple cancer cell lines including HT29, HCT116, PC3, and HeLa." (PMID 28599312, 2017).